MIR6504 (microRNA 6504)
Synonyms: hsa-mir-6504
Gene: MicroRNA gene on chromosome 16 (81,611,348 to 81,611,408, forward strand). Ensembl gene ENSG00000275109.
Homologues: Orthologues: chimpanzee MIR6504 (100% identical).